CYP2C8 (cytochrome P450 family 2 subfamily C member 8)
Description:
A cytochrome P450 monooxygenase involved in the metabolism of various endogenous substrates, including fatty acids, steroid hormones and vitamins. Mechanistically, uses molecular oxygen inserting one oxygen atom into a substrate, and reducing the second into a water molecule, with two electrons provided by NADPH via cytochrome P450 reductase (NADPH--hemoprotein reductase). Primarily catalyzes the epoxidation of double bonds of polyunsaturated fatty acids (PUFA) with a preference for the last double bond. Catalyzes the hydroxylation of carbon-hydrogen bonds. Metabolizes all trans-retinoic acid toward its 4-hydroxylated form. Displays 16-alpha hydroxylase activity toward estrogen steroid hormones, 17beta-estradiol (E2) and estrone (E1). Plays a role in the oxidative metabolism of xenobiotics. It is the principal enzyme responsible for the metabolism of the anti-cancer drug paclitaxel (taxol).
Synonyms: CPC8; CYP2C8DM; CYPIIC8; MP-12/MP-20
Tractability: Small molecule: a structure with a bound ligand is known; it has a high-quality binding pocket; it belongs to a druggable protein family. Antibody: its Gene Ontology location is reachable by antibodies, with high confidence; UniProt places it where antibodies can reach, with medium confidence. PROTAC: its protein half-life has been measured; a small molecule that binds it is known.
Target class: Cytochrome P450 family 2C; Cytochrome P450; Enzyme; Cytochrome P450 family 2; Cytochrome P450 2C8
Safety:
Unwanted effects reported when the protein is acted on. In parentheses: how it was acted on, where the effect was seen, and who reports it.
anemia (source: ClinPGx)
better kidney function (source: ClinPGx)
kidney dysfunction (source: ClinPGx)
leukopenia (source: ClinPGx)
neurotoxicity (source: ClinPGx)
osteonecrosis of the jaw (source: ClinPGx)
side effects (source: ClinPGx)
thrombocytopenia (source: ClinPGx)
weight gain and edema (source: ClinPGx)
Gene: Protein-coding gene on chromosome 10 (95,034,359 to 95,069,498, reverse strand). Ensembl gene ENSG00000138115.
Subcellular location: Endoplasmic reticulum membrane; Microsome membrane
Subcellular location (Human Protein Atlas): Vesicles; Plasma membrane
Pathways (Reactome):
Metabolism: Biosynthesis of maresin-like SPMs; CYP2E1 reactions; Synthesis of (16-20)-hydroxyeicosatetraenoic acids (HETE); Synthesis of epoxy (EET) and dihydroxyeicosatrienoic acids (DHET); Xenobiotics
Drug ADME: Aspirin ADME
Gene Ontology:
Molecular function: arachidonate epoxygenase activity; caffeine oxidase activity; estrogen 16-alpha-hydroxylase activity; monooxygenase activity; oxidoreductase activity, acting on paired donors, with incorporation or reduction of molecular oxygen, reduced flavin or flavoprotein as one donor, and incorporation of one atom of oxygen; protein binding; retinoic acid 4-hydroxylase activity; heme binding; arachidonate 11,12-epoxygenase activity; arachidonate 14,15-epoxygenase activity; iron ion binding; oxidoreductase activity, acting on paired donors, with incorporation or reduction of molecular oxygen
Biological process: epoxygenase P450 pathway; estrogen metabolic process; icosanoid biosynthetic process; lipid hydroxylation; oxidative demethylation; retinoic acid metabolic process; steroid metabolic process; xenobiotic catabolic process; xenobiotic metabolic process; long-chain fatty acid biosynthetic process; omega-hydroxylase P450 pathway; arachidonate metabolic process; monocarboxylic acid metabolic process; retinol metabolic process; terpenoid metabolic process
Cellular component: cytoplasm; endoplasmic reticulum membrane
Genetic constraint (gnomAD): Loss-of-function variants: 53 observed, 44.34 expected, observed/expected ratio (o/e) 1.2, 90% interval 0.96 to 1.5. The upper end of that interval is the gene's LOEUF score, 1.5, which puts it in group 6 of 6, group 1 being the genes least tolerant of losing a copy. Missense variants: 651 observed, 610.51 expected, observed/expected ratio (o/e) 1.07, 90% interval 1 to 1.14. Synonymous variants: 218 observed, 217.51 expected, observed/expected ratio (o/e) 1, 90% interval 0.9 to 1.12.
Homologues: Orthologues: chimpanzee CYP2C8 (98% identical), macaque CYP2C19 (93% identical), macaque CYP2C93 (84% identical). Paralogues in human: CYP2C19 (78% identical), CYP2C9 (78% identical), CYP2C18 (77% identical), CYP2E1 (57% identical), CYP2A13 (51% identical), CYP2B6 (50% identical), CYP2F1 (50% identical), CYP2A6 (49% identical), CYP2A7 (49% identical), CYP2S1 (43% identical), CYP2D6 (41% identical), CYP2J2 (41% identical), and 3 more.
Diseases named in the same sentence as CYP2C8 in open-access papers:
CYP2C8 is named in the same sentence as 91 diseases in open-access papers, as found by Europe PMC text mining. Sharing a sentence is not in itself a finding about the gene and the disease. The quoted sentences say what the papers report.
breast carcinoma (28 papers, 2004 to 2024). "A lower paclitaxel clearance has been demonstrated in CYP2C8*3 carrier patients with ovarian cancer than in non-carriers, and in contrast, increased paclitaxel-metabolizing activity was attributed to CYP2C8*3 allele in breast cancer patients." (PMID 37686184, 2023). "Another investigation suggested that the rs1058930 polymorphism of CYP2C8 (CYP2C8*4) affects lymph node status of breast cancer patients." (PMID 23226154, 2012). "We then investigated the association between CYP2C8/9 haplotypes in relation to early breast cancer events (local, regional, new breast cancer, distant metastases, or death from breast cancer) by December 2008." (PMID 19935798, 2009). "We found that an increasing number of CYP2C8/9 *3/*1/*2/*1 haplotype alleles and especially CYP2C8*3 alleles was associated with increased hazard of early breast cancer-related events in tamoxifen-treated patients." (PMID 19935798, 2009). "Several genetic polymorphisms in CYP2C8 may influence survival after cancer diagnosis due to their role in the metabolism of various breast cancer chemotherapy drugs." (PMID 30148168, 2018). "We have reported the diversity of polymorphism frequencies for the CYP2D6, CYP3A5, CYP2C8, and IL-10 genes in breast cancer patients from Mexico and Spain and classified them by metabolic activity for chemotherapy but no specific function has been described for these polimorphisms." (PMID 29997359, 2018). "Thus, additional in vivo studies are needed to gauge what impact, if any, CYP2C8 polymorphisms have on clinical outcomes in postmenopausal breast cancer patients taking EXE." (PMID 28603633, 2017). "CYP2C8/9 polymorphisms may influence breast cancer-free survival after diagnosis due to their role in the metabolism of tamoxifen, paclitaxel, and other chemotherapy." (PMID 19935798, 2009). "This is not fully compatible with our finding, as we found both a higher frequency of nodal involvement with the CYP2C8/9 *3/*1/*2/*1 genotype (in tumours larger than 20 mm) and a higher risk of any type of breast cancer recurrence, especially in women treated with tamoxifen." (PMID 19935798, 2009). "Moreover, the CYP2C8*3 allele was associated with early breast cancer-related events in women treated with tamoxifen." (PMID 19935798, 2009). "On the other hand, authors from Iran found the association between CYP19A1 (rs749292) (also for CYP2C8 (rs1058930), CYP1B1 (rs1056836)) genes’ polymorphisms and increased risk of breast cancer in women in Mazandaran province." (PMID 35160095, 2022). "The abnormal expression of the CYP2C8 gene is involved in the progression of many human cancers, such as hepatocellular carcinoma, breast cancer, prostate cancer, and endometrial tumor." (PMID 36246885, 2022). "We find that SPIN1 increases breast cancer Adriamycin resistance via enhancing the expression of drug metabolizing enzymes and transporter CYP2C8, UGT2B4, UGT2B17 and ABCB4." (PMID 29743122, 2018). "In comparison to CYP3A4, CYP2C8 transcripts were detected at variable levels in our breast carcinoma samples and were preferentially high in tumors with low proliferation rates, as indicated by low Ki67 scores." (PMID 23935969, 2013). "We studied the association of the functionally significant variant alleles of CYP3A4, CYP3A5, CYP2B6, CYP2C8, CYP2C9 and CYP2C19 with the clinical response to neoadjuvant chemotherapy in breast cancer patients." (PMID 22702493, 2012). "Here, we studied the association of functionally significant variant alleles of CYP3A4, CYP3A5, CYP2B6, CYP2C8, CYP2C9 and CYP2C19 with the clinical response to neoadjuvant chemotherapy in breast cancer patients." (PMID 22702493, 2012). "The CYP2C8 enzyme is involved in paclitaxel metabolism, but only one woman with a breast cancer-related event had been treated with a paclitaxel-based regimen and four other women with events had received a docetaxel-based regimen as neoadjuvant treatment." (PMID 19935798, 2009).
breast carcinoma (continued). "Even if the PGx heterogeneity is present in the cohort of breast cancer patients, it does not directly influence the risk of neuropathy beyond the contribution of CYP2C8*3." (PMID 27304055, 2016). "Several genetic polymorphisms in genes such as cytochrome-P450 (CYP)2C8 and CYP2C9, may influence survival after cancer diagnosis due to their role in the metabolism of various breast cancer drugs, including tamoxifen and chemotherapy." (PMID 19935798, 2009). "Additionally, CYP2C8 and CYP3A4 are high involved in the metabolism of paclitaxel in patients with ovarian cancer, while breast cancer patients carrying the *3 variant of CYP2C8 have better response to paclitaxel, but at an increase in peripheral neurotoxicity." (PMID 27047539, 2016). "Data from PPISURV and GOBO revealed that breast cancer patients with high expression of ABCB4 (P = 0.0242), CYP2C8 (P = 0.02028), UGT2B4 (P = 0.0181) or UGT2B17 (P = 0.00815) showed poorer survival than those with low expression." (PMID 29743122, 2018). "Altogether these data indicate that the expression of the drug metabolizing enzymes CYP2C8, UGT2B4 and UGT2B17, and transporter ABCB4 was positively regulated by SPIN1 in breast cancer." (PMID 29743122, 2018). "SPIN1 is identified as a novel target of the miR-148/152 family and enhances Adriamycin resistance by regulating drug metabolizing enzymes and transporter CYP2C8, UGT2B4, UGT2B17 and ABCB4 in breast cancer." (PMID 29743122, 2018). "Eltrombopag is a substrate of several drug-metabolizing enzymes, including cytochrome P450 (CYP) 1A2, CYP2C8, uridine diphosphate-glucuronosyltransferase (UGT) 1A1, and UGT1A3, and the agent is also a substrate of breast cancer resistance protein." (PMID 22674141, 2012). "Tamoxifen is a moderate CYP2C8 inhibitor, a CYP2C9 substrate, and significantly inhibits CYP2C9 activity in breast cancer patients." (PMID 19935798, 2009). "Another study showed that, polymorphisms variants of CYP2C8*2, CYP2C8*3, CYP2C9*2, CYP2C9*3genes showed there was a negative association with therapeutic response towards neo-adjuvant chemotherapy in breast cancer patients." (PMID 40092865, 2024). "Critically, certain drugs used to treat advanced stages of breast cancer such as paclitaxel display little or no cytotoxic activity after metabolism by CYP2C8 and CYP3A4." (PMID 33809117, 2021). "CYP epoxygenases, including CYP2C8, 2J2, 2C9, and CYP3A4, have the capacity to synthesize EETs and may be involved in breast cancer progression." (PMID 29050342, 2017). "We found that expressions of certain CYP genes is correlated with node status (N stage) of breast cancer including CYP2A6 (p-value = 0.025), CYP2C8 (p-value = 0.035), CYP2D6 (p-value = 0.027), CYP2J2 (p-value = 0.036), CYP3A7 (p-value = 0.026), and CYP4B1 (p-value = 0.046)." (PMID 28684774, 2017). "Since the LD between CYP2C8*3 and CYP2C9*2 was incomplete, we also examined the effect of each SNP separately in the model, and while CYP2C8*3 was associated with significant increased hazard of early breast cancer-related events, CYP2C9*2 was associated with non-significant decreased hazard." (PMID 19935798, 2009). "Expression of CYP2C8/9 and CYP2J2, and/or high level of 14,15-EET detected in patients were found to be positively correlated with aggressiveness of human BC, or that might be involved in breast cancer cell epithelial-mesenchymal transition and cisplatin resistance." (PMID 31072371, 2019).
neuropathy (11 papers, 2015 to 2025). A disorder affecting the nervous system that manifests with pain, tingling, numbness, and/or muscle weakness. "It is reported that individuals carrying low-metabolism variants (CYP2C8*2, CYP2C8*3, or CYP2C8*4) experienced grade 2 or higher neuropathy at lower cumulative paclitaxel doses." (PMID 39598531, 2024). "To summarize, CYP2C8, encoding one of the main metabolizing enzymes of paclitaxel, warrants further validation as a predictor for paclitaxel-induced neuropathy." (PMID 32351390, 2020). "In contrast, ABCB1, CYP1B1, and CYP2C8 gene mutations were associated with paclitaxel-induced neuropathy." (PMID 28620280, 2017). "Showed that there is a low-activity variant of the main paclitaxel metabolizing enzyme (CYP2C8*3) that has been shown to be associated with increased paclitaxel effectiveness and neuropathy." (PMID 28898275, 2017). "The polymorphism CYP2C8*3 gene (rs10509681) has been found to be related to a decrease in the metabolic activity of paclitaxel, and associated with potential increases in neuropathy risk." (PMID 29163177, 2017). "ABCC2 and GSTP1 were associated with both platinum- and taxane-induced neuropathy; CYP2C8 was associated with both taxane- and platinum/taxane-induced neuropathy; and ERCC1 was associated with platinum- and platinum/taxane-induced neuropathy." (PMID 26269716, 2015). "In addition to the two, the SNV in CYP2C8*3 was associated with risk of neuropathy without reaching statistical significance." (PMID 26763541, 2016). "Finally, in breast cancer patients treated with paclitaxel, CYP2C8*3 status was significantly associated with an increased risk of paclitaxel-induced neuropathy (P = .006); each CYP2C3*8 allele approximately doubled a patient’s risk of developing grade ≥2 neuropathy (P = .004)." (PMID 25596818, 2015). "On the other hand, CYP2C8, ABCB1, EPHA5, EPHA6 and TUBB2A were found to be associated with taxane-induced neuropathy in more than one study, but not to be associated with platinum-induced neuropathy." (PMID 26269716, 2015).
diabetes (9 papers, 2017 to 2025). "SHAP analysis identified chemotherapy dosage, nerve magnetic resonance imaging abnormalities, electrocardiogram changes, CYP2C8 mutations, and diabetes as the most influential predictors." (PMID 40765998, 2025). "The CYP2C8*3 variants regulate the dosage of the diabetes drugs rosiglitazone and repaglinide." (PMID 30409984, 2018). "Another study in India indicated the variable distribution of CYP2C8 and CYP2C9 allelic polymorphisms in people with diabetes." (PMID 31088900, 2019). "While limitations must be presently acknowledged regarding UMs and PMs, this might be the start of an activity score assignment for CYP2C8 in future diabetes treatments." (PMID 40426982, 2025). "Our study investigated the expression of IL-1β, IL-10, CYP2C8, CYP2C9, CYP2J2 and sEH in HBCs from patients with type 1 diabetes mellitus (T1DM) and gestational diabetes mellitus (GDM) compared to healthy controls using immunohistochemistry." (PMID 38590527, 2024). "Because EETs seem to play a role in the pathophysiology of diabetes, the aim of this study was to describe the expression profiles of EET-generating (CYP2C8, CYP2C9, CYP2J2) and EET-degrading (sEH) enzymes in HBCs from patients with T1DM and GDM compared to healthy controls." (PMID 38590527, 2024). "Of relevance, many diabetes drugs are metabolized by CYP2C9, CYP3A4, and CYP2C8." (PMID 36285162, 2022).
hepatocellular carcinoma (9 papers, 2013 to 2025). A malignant tumor that arises from hepatocytes. "According to our results, we cautiously drew the conclusion that downregulation of CYP2A6 and CYP2C8 in tumor tissues is linked to worse overall survival and recurrence-free survival from hepatocellular carcinoma." (PMID 30148168, 2018). "For example, Cyp2c6 is rapidly induced by glucocorticoids in rat hepatoma cells, and is a close homolog of human Cyp2c8 and Cyp2c9 implicated in eicosanoid production." (PMID 23642095, 2013). "The genes of cytochrome P450 have been widely studied in hepatocellular carcinoma and many other cancer types, and CYP2C8 is a relatively novel candidate in hepatocellular carcinoma." (PMID 31722693, 2019). "Furthermore, the two human homologous genes of Cyp2c29, Cyp2C8 and Cyp2C9, are down-regulated during the progression of human hepatocellular carcinoma." (PMID 40423332, 2025). "CYP2C8 can be regulated by GAS5/miR-382-3p in hepatocellular carcinoma and play an anticancer role." (PMID 35265613, 2022). "Moreover, the CYP2C8 gene expression level was confirmed as a potential prognostic marker for hepatocellular carcinoma after hepatectomy." (PMID 32851080, 2020). "Indeed, previous in vivo and in vitro studies, including ours, have shown that CYP2C8, 2C9, and 2JC promote cancer cell proliferation, migration, angiogenesis, survival and invasion in several types of cancer such as hepatocellular carcinoma, esophageal carcinoma, and malignant hematologic disease." (PMID 25406731, 2014). "For example, ARG1, CYP2C8, CYP3A4, CYP3A7 and CYP4A11, which we identified using MOG as decreasing expression with LIHC progression, have each been recently studied as prognostic markers for hepatocellular carcinoma." (PMID 31956905, 2020).